ALOX12 (arachidonate 12-lipoxygenase, 12S type)
Diseases named in the same sentence as ALOX12 in open-access papers (continued):
Sharing a sentence is not in itself a finding about the gene and the disease.
tumor (continued). "In the present study, we found that ALOX12–12-HETE was activated during liver IRI and its activation was enhanced in fatty liver, which induced more severe tumor recurrence in fatty liver than normal liver." (PMID 31831037, 2019). "The RT-qPCR result revealed that ALOX12 was markedly up-regulated (P=0.0144) and RMND5B was markedly down-regulated (P=0.0016) in tumor samples compared with controls, while the expression of CTSC was not notably different (P=0.7259) between tumor and control samples." (PMID 38903709, 2024). "When we transfected MCF-7 and FaDu cells with WT-ALOX12 and WT-FKBP5 genes, the recreated overexpression of ALOX12 and FKBP5 led to the induction of cellular death, inhibition of cellular invasion abilities, and strong inhibition of xenograft tumor growth." (PMID 39766798, 2024). "To confirm the contribution of ALOX12 to the tumor suppression activity of TPCI, we tested whether inhibiting ALOX12 activity could affect TPCI-mediated tumor cell growth on HeLa-cells-xenografted nude mice model." (PMID 36517470, 2022). "Specifically, our in vitro results suggest that ALOX5 may be an oncogene, while ALOX12 and CISD1 may be tumor suppressor genes in PAAD." (PMID 35033072, 2022). "Remarkably, modulating the expression of ALOX12 in HeLa cells had no obvious effect on the anti-tumor efficiency of MB treatment, suggesting that ALOX12 did not contribute to the MB treatment-induced apoptosis." (PMID 36517470, 2022). "ALOX12, a member of the lipoxygenase family, is upregulated in CRC tissues and promotes the production of tumor stromal vascular endothelial growth factor, resulting in angiogenesis and tumor metastasis." (PMID 34868393, 2021). "When overexpressed in tumor cells in xenograft models, SAT1 limits tumor growth through ferroptosis induction, which was later shown to be additionally dependent on the lipoxygenase ALOX12." (PMID 34639222, 2021). "We demonstrated the important role of ALOX12–12-HETE-GPR31 in HCC recurrence, which may provide a potential therapeutic target to reduce the tumor recurrence in NAFLD after liver transplantation." (PMID 31831037, 2019). "However, the role of ALOX12–12-HETE in HCC as well as tumor recurrence has not been investigated." (PMID 31831037, 2019).
cancer (28 papers, 2014 to 2025). A tumor composed of atypical neoplastic, often pleomorphic cells that invade other tissues. "ALOX12 plays an important role in inflammation and oxidation, while abnormal DNA methylation and genetic variants of ALOX12 are associated with various human diseases and pathological phenotypes, including cancer." (PMID 33540700, 2021). "Many human cancers are noted to have a loss of one copy of ALOX12 on chromosome 17p, and variants in ALOX12 have also been associated with human SCCs." (PMID 34890228, 2021). "Our results clearly indicate that psychological stress may induce cancer development via increased somatic missense mutations in ALOX12 and FKBP5 genes." (PMID 39766798, 2024). "Our results are in alignment with this report because we found ALOX12 and FKBP5 somatic mutations in cancer patients who had experienced traumatic life events." (PMID 39766798, 2024). "Various human cancer types can ectopically express ALOX12 including breast, prostate, esophageal, gastric, and renal cancers as well as melanoma." (PMID 36754910, 2023). "ALOX12, as a ferroptosis driver gene, has been reported to be expressed aberrantly in several cancers." (PMID 36851083, 2023). "As expected, both of the ALOX12-knockdown cancer cells were resistant to ferroptosis induced by TPCI upon irradiation." (PMID 36517470, 2022). "The ALOX12 gene resides on human chromosome 17p13.1 at a common position with frequent monoallelic deletion in human cancers." (PMID 34131139, 2021). "By inactivating ALOX12, cancer cells can escape ROS-mediated ferroptosis." (PMID 41210681, 2025). "For example, ALOX12 was seen to promote ferroptosis in cancer cells, while the ALOX15 was seen to have a role in mediating RSL3-induced ferroptosis in various cells, including neurons, and ALOX5 was also observed to be activated in erastin and RSL3-induced ferroptosis in cancer cells." (PMID 39721496, 2025). "ALDOB and ALOX12 have been reported to be involved in fructose-induced cancer metastasis." (PMID 38200154, 2024). "These ALOX12 and FKBP5 somatic missense mutations may be induced via the psychological stress experienced by these patients, which may also contribute to cancer initiation and progression." (PMID 39766798, 2024). "As a comparison, TPCI not only inhibits GPX4 pathway, but more importantly, is capable of generating a large amount of lipid ROS through ALOX12 activation, so that it holds great potential to be universally applicable on the treatment of a large variety of cancers." (PMID 36517470, 2022). "Many studies indicate the abnormal expression of ALOX12 in tumors, suggesting that ALOX12 may be a potential marker for many varieties of cancers." (PMID 35033072, 2022). "Given that ALOX12 usually functions in many types of cancer cells, the discovery of TPCI as a photo-induced ALOX12 activator renders a viable therapeutic approach on the basis of distinct ferroptosis of cancer cells, without limiting to their intrinsic ACSL4 expression levels." (PMID 36517470, 2022).
cancer (continued). "Importantly, ALOX12 gene is frequently deleted in human cancers." (PMID 33000412, 2021). "Indeed, the levels of the oxidized phosphatidylethanolamine (PE) and phosphatidylcholine (PC) (oxPE (18:0/22:4)sn2 or oxPC (18:0/20:4)sn2) were significantly induced upon ALOX12 expression, indicating that ALOX12 is critical for generating oxidized PE and oxidized PC in human cancer cells." (PMID 34131139, 2021). "We first searched the Protein Atlas to understand ALOX12 and FKBP5 expression status in cancer cell lines and cancer tissues." (PMID 39766798, 2024). "This is because, in cancer patients, the A549, MCF-7, and FaDu cell lines express lower levels of ALOX12 and FKBP5 mRNAs when compared to the cancer-free patient group, as indicated in our qRT-PCR results." (PMID 39766798, 2024). "The Protein Atlas also shows that ALOX12 and FKBP5 have low expression both in cancer tissue and cancer cell lines." (PMID 39766798, 2024). "It has been reported that ALOX12 and 12-HETE mediate cancer proliferation, survival, and metastasis." (PMID 39766798, 2024). "The lipoxygenase ALOX12 produces 12-HETE, which induces inflammation and promotes cancer progression." (PMID 38200154, 2024). "The relationship between cancer and FKBP5 and ALOX12 gene expression has been evaluated in several studies, and the results support our findings." (PMID 39766798, 2024). "It is also interesting that ALOX12 belongs to the IFN-regulated genes, suggesting a potential immune mechanism for its upregulation in cancers." (PMID 36754910, 2023). "The results showed that ALOX12, ANGPTL7, DRD4, and MAPK9 remarkably decreased within ESCC samples relative to non-carcinoma samples, whereas SLC38A1 and ZNF419 were highly expressed." (PMID 34291083, 2021). "We have showed that TPCI can activate ALOX12 upon irradiation and enhance lipid ROS accumulation, hence promoting ferroptosis of cancer cells that does not require ACSL4." (PMID 36517470, 2022). "The TPCI-induced ALOX12 activation resulted in direct peroxidation of PUFAs into lethal lipid ROS, which then accumulated and triggered cancer cells ferroptosis without the participation of ACSL4." (PMID 36517470, 2022). "Since the intrinsic modulators that contribute to ALOX12 activation remain largely unknown, a designed ALOX12 activator becomes indispensable and hence holds great promise to promote ACSL4-independent ferroptosis of cancer cells." (PMID 36517470, 2022). "As ALOX12 is highly expressed in cancer cells and no ALOX12 activator has been reported so far, our study unveiling TPCI-induced ALOX12 activation should broaden the applicability of ferroptosis in cancer therapy." (PMID 36517470, 2022). "The expression status of ALOX12 and FKBP5 genes in patients with or without cancer and several cancer cell lines was also examined using the qRT-PCR method." (PMID 39766798, 2024). "The expression status of ALOX12 and FKBP5 genes in patients with or without cancer and several cancer cell lines demonstrated that both ALOX12 and FKBP5 mRNA levels were downregulated in cancer patients and cancer cell lines (A549, MCF-7, and FaDu)." (PMID 39766798, 2024). "The expression status of ALOX12 and FKBP5 genes on patients with or without cancer and several cancer cell lines demonstrated that both ALOX12 and FKBP5 mRNA levels were downregulated only in cancer patients and cancer cell lines but not in cancer free control groups." (PMID 39766798, 2024). "Therefore, our study identifies TPCI as the first ALOX12 activator to induce ferroptosis independent of ACSL4, which renders a viable therapeutic approach on the basis of distinct ferroptosis of cancer cells, regardless their ACSL4 expressions." (PMID 36517470, 2022).
neurodegenerative disease (4 papers, 2022 to 2026). A disorder of the central nervous system characterized by gradual and progressive loss of neural tissue and neurologic function. "The common feature for all tested anti-inflammatory plant extracts was related to the downregulation of the ALOX12 gene, which is associated with the neuroprotective action of these medicinal plants and their potential benefits in neurodegenerative diseases." (PMID 40006074, 2025). "ALOX12 metabolizes arachidonic acid and other polyunsaturated fatty acids to corresponding lipid hydroxides that participate in the pathogenesis of neurodegenerative diseases." (PMID 38474262, 2024).
lung (1 paper, 2024). "Notably, after genetically inhibiting Alox12 in mice, ferroptosis was dramatically inhibited compared with that in WT mice subjected to lung IR, as evidenced by decreases in ferric iron deposits, the levels of Fe2+ and MDA, and the increases in the GSH/GSSG ratio and the protein level of GPX4." (PMID 39268501, 2024).
neurodevelopmental disorder (1 paper, 2020). A behavioral and cognitive disorder with onset during the developmental period that involves impaired or aberrant development of intellectual, motor, or social functions. "In this study, we found that Ptgs2, as well as Alox12 expression were significantly increased in the brains of MIA-offspring, supporting the role of these enzymes in neurodevelopmental disorders." (PMID 32521803, 2020).
peripheral neuropathy (1 paper, 2025). A disorder affecting the peripheral nervous system. "SNPs in ALOX12 have been associated with peripheral neuropathy and menstrual dysfunction and have already been identified." (PMID 40647337, 2025).
vascular disorder (1 paper, 2023). A general term used to describe any disease affecting blood vessels]. "There are six known functional LOX genes in humans (ALOX5, ALOX12, ALOX12B, ALOX15, ALOX15B, ALOXE3), but only three of them, 5-LOX, 12-LOX (platelet-type), and 15-LOX (reticulocyte-type), appear to be important for vascular disorders." (PMID 36675152, 2023).
ALOX12 also shares sentences with these, for which no sentence is quoted: infection (6 papers); COVID-19 (4); type 2 diabetes (3); clear cell renal cell carcinoma (2); diabetic kidney disease (2); gastric cancer (2); neurological disorders (2); psoriasis (2); vitiligo (2); alcohol abuse (1); Alcoholism (1); Alzheimer disease (1); aneurysm (1); brain injury (1); cardiomyopathy (1); cardiovascular disease (1); Cerebral ischemia (1); chronic lymphocytic leukemia (1); Cirrhosis (1); congenital toxoplasmosis (1); dyslipidaemia (1); endothelial dysfunction (1); esophageal cancer (1); Eμ- (1); fibrosis (1); gastric adenocarcinoma (1); glioma (1); Glucose intolerance (1); head and neck carcinoma (1); heart injury (1).
A further 19 diseases each share a sentence with ALOX12 in 1 paper.